PIWIL4 (piwi like RNA-mediated gene silencing 4)
Description:
Plays a central role during spermatogenesis by repressing transposable elements and preventing their mobilization, which is essential for the germline integrity (By similarity). Acts via the piRNA metabolic process, which mediates the repression of transposable elements during meiosis by forming complexes composed of piRNAs and Piwi proteins (By similarity). The PIWIL4-piRNA pathway acts in the nucleus and mediates silencing of active transposons: engages with nascent transposable element transcripts and governs the piRNA-directed DNA methylation and subsequent repression of transposons (By similarity). In contrast to PIWIL1 and PIWIL2, does not show endonuclease activity (By similarity). Directly binds piRNAs, a class of 24 to 30 nucleotide RNAs that are generated by a Dicer-independent mechanism and are primarily derived from transposons and other repeated sequence elements (By similarity). Associates with secondary piRNAs antisense and PIWIL2/MILI is required for such association (By similarity). The piRNA process acts upstream of known mediators of DNA methylation (By similarity). Plays a key role in the piRNA amplification loop, also named ping-pong amplification cycle, by acting as a 'slicer-incompetent' component that loads cleaved piRNAs from the 'slicer-competent' component PIWIL2 and target them on genomic transposon loci in the nucleus (By similarity). May be involved in the chromatin-modifying pathway by inducing 'Lys-9' methylation of histone H3 at some loci. In addition to its role in germline, PIWIL4 also plays a role in the regulation of somatic cells activities (By similarity). Plays a role in pancreatic beta cell function and insulin secretion (By similarity). Involved in maintaining cell morphology and functional integrity of retinal epithelial through Akt/GSK3alpha/beta signaling pathway. When overexpressed, acts as an oncogene by inhibition of apoptosis and promotion of cells proliferation in tumors.
Synonyms: HIWI2; FLJ36156; Miwi2
Tractability: PROTAC: ubiquitination databases record sites on it.
Gene: Protein-coding gene on chromosome 11 (94,543,840 to 94,621,421, forward strand). Ensembl gene ENSG00000134627.
Subcellular location: Nucleus; Cytoplasm
Subcellular location (Human Protein Atlas): Mitochondria; Nucleoplasm
Pathways (Reactome):
Gene expression (Transcription): PIWI-interacting RNA (piRNA) biogenesis; Regulation of endogenous retroelements by Piwi-interacting RNAs (piRNAs)
Gene Ontology:
Molecular function: piRNA binding; RNA endonuclease activity; nucleic acid binding; RNA binding
Biological process: epithelial structure maintenance; piRNA processing; secondary piRNA processing; spermatogenesis; transposable element silencing by heterochromatin formation; transposable element silencing by piRNA-mediated DNA methylation
Cellular component: cytoplasm; nucleoplasm; nucleus; P granule; piP-body
Genetic constraint (gnomAD): Loss-of-function variants: 49 observed, 86.08 expected, observed/expected ratio (o/e) 0.57, 90% interval 0.45 to 0.72. The upper end of that interval is the gene's LOEUF score, 0.72, which puts it in group 2 of 6, group 1 being the genes least tolerant of losing a copy. Missense variants: 786 observed, 967.45 expected, observed/expected ratio (o/e) 0.81, 90% interval 0.76 to 0.86. Synonymous variants: 309 observed, 345.11 expected, observed/expected ratio (o/e) 0.9, 90% interval 0.81 to 0.98.
Homologues: Orthologues: chimpanzee PIWIL4 (99% identical), macaque PIWIL4 (98% identical), rabbit PIWIL4 (83% identical), dog PIWIL4 (82% identical), pig PIWIL4 (81% identical), rat Piwil4 (78% identical), mouse Piwil4 (77% identical), guinea pig PIWIL4 (67% identical), tropical clawed frog piwil4 (58% identical), Drosophila melanogaster aub (33% identical), Drosophila melanogaster piwi (32% identical), Caenorhabditis elegans prg-1 (30% identical). Paralogues in human: PIWIL1 (50% identical), PIWIL3 (40% identical), PIWIL2 (36% identical).
Diseases named in the same sentence as PIWIL4 in open-access papers:
PIWIL4 is named in the same sentence as 60 diseases in open-access papers, as found by Europe PMC text mining. Sharing a sentence is not in itself a finding about the gene and the disease. The quoted sentences say what the papers report.
glioma (23 papers, 2017 to 2025). A benign or malignant brain and spinal cord tumor that arises from glial cells (astrocytes, oligodendrocytes, ependymal cells). "PiR-598, piR-8041, piR-DQ590027, piR-DQ593109, PIWIL1, PIWIL2, PIWIL3, and PIWIL4 may all be involved in the pathogenesis of glioma, and could be diagnostic markers for glioma." (PMID 33109195, 2020). "Among the model genes, CRNDE, a long non-coding RNA, is upregulated in various solid tumors and promotes malignant progression of glioma by regulating the miR-384/PIWIL4/STAT3 axis." (PMID 40130175, 2025). "PIWIL4 has been shown to promote neuronal differentiation in stem cell models and modulate glioma-related factors such as PTN and NLGN3." (PMID 41228218, 2025). "A similar study found that miR‐384 inhibited the malignant progression of glioma by inhibiting PIWIL4 expression by targeting its 3′‐UTR region, while miR‐331‐3p downregulated E2F1 expression and promoted the proliferation and migration of hepatoma cells." (PMID 32892482, 2020). "In contrast, PIWIL3 exhibited a protective effect in glioma cells, and low expression of PIWIL4 has been found in tumor cells from hepatocellular carcinoma, breast cancer and non-small cell lung cancer." (PMID 32357464, 2020). "Special findings were reported that CRNDE overexpression in glioma resulted in decreased protein level of piwi-like RNA-mediated gene silencing 4 (PIWIL4)." (PMID 32435153, 2020). "The results of this study were consistent with earlier research, in which miR-384 regulates the expression of PIWIL4 and then influence expression of apoptosis-related proteins, thus exerting pro-apoptotic effects in glioma cells." (PMID 31165722, 2019). "Recently, it was reported that miR-384 exerted tumor-suppressive functions by binding to the 3′UTR of PIWIL4 in glioma." (PMID 30186040, 2018). "CRNDE can promote the malignant progress of glioma by lessening miR-384/PIWIL4/STAT3 Axis, miR-186 or mTOR signaling pathways." (PMID 29088774, 2017). "Consistently, CRNDE promoted hepatic carcinoma cell proliferation, invasion and migration by sponging miR-384, and CRNDE also promoted malignant progression of glioma by attenuating miR-384/PIWIL4/STAT3 axis." (PMID 29299168, 2017). "CRNDE could promote the malignant progression of glioma by attenuating the miR-384/PIWIL4/STAT3 axis." (PMID 37152037, 2023). "Additionally, it has been observed to promote glioma growth and invasion via mTOR signalling and to promote malignant progression by attenuating the miR-384/PIWIL4/STAT3 axis, in accordance with our results." (PMID 35311131, 2022). "The CRNDE promotes malignant progression of glioma by acting as a ceRNA sponge for miR-384 and inhibiting the activation of miR-384 target piwi-like RNA-mediated gene silencing 4 (PIWIL4) and its downstream protein signal transducer and activator of transcription 3 (STAT3)." (PMID 33800703, 2021). "The miR-384/PIWIL4/STAT3 axis has an important role in pathogenesis of glioma." (PMID 33109195, 2020). "Both CRNDE knock-down or miR-384 up-regulation led to a decrease in PIWIL4 in glioma." (PMID 33109195, 2020). "In addition, Bcl-2, Bcl-xL and caspase 3 were also the downstream of PIWIL4 and thence CRNDE could interfere with glioma cells apoptosis through CRNDE-miR-384-PIWIL4 axis." (PMID 32435153, 2020). "In glioma, CRNDE was upregulated and promote tumor progression via attenuating miR-384/PIWIL4/STAT3 axis, it also contributed to temozolomide (TMZ) resistance by autophagy, knockdown of CRDNE enhanced TMZ chemosensitivity." (PMID 36281290, 2022). "CRNDE has been reported to promote the proliferation, migration, and invasion of glioma through attenuating miR-384/PIWIL4/STAT3 axis and facilitating EGFR activation to modulate glioma growth." (PMID 36033510, 2022). "Knockdown of CRNDE promotes the miR-348 expression, leading to inhibition of piwi-like RNA-mediated gene silencing 4 (PIWIL4), which has an oncogenic role in glioma, thus inhibiting the malignant progression of glioma." (PMID 33980320, 2021).
glioma (continued). "Moreover, through attenuating the miR-384/PIWIL4/STAT3 axis, CRNDE promotes malignant progression in glioma cells." (PMID 34454479, 2021). "As research continues, an increasing interest in the function of CRNDE in glioma reveals that CRNDE could modulate glioma cell growth and invasion with EGFR activation and through mTOR signaling, and promote malignant progression by attenuating miR-384/PIWIL4/STAT3 axis in GBM." (PMID 34454479, 2021).
breast cancer (21 papers, 2012 to 2025). A primary or metastatic malignant neoplasm involving the breast. "In breast cancer, PIWIL4 shows marked overexpression in primary tumors and the MDA-MB-231 cell line." (PMID 41208974, 2025). "PIWIL4 Gene is one of the upregulated genes in breast cancer which is highly expressed not only in breast cell lines but also in breast cancer samples." (PMID 32211149, 2020). "This reduction of the cell motility by PIWIL4 downregulation has previously been described in breast cancer cells through an impairment of Vimentin and N-Cadherin." (PMID 32357464, 2020). "Encoding an argonaute family protein, the piwi-like protein 4 (PIWIL4) gene was reported to be highly expressed in breast cancer cells, and its knockdown was found to lessen leukemic growth." (PMID 31892232, 2019). "PIWIL4 promotes cell division, migration and survival of breast cancer by activating TGF-β, MAPK/ERK, and FGF signaling pathways." (PMID 31727866, 2019). "Reports on the clinical significance of PIWIL3 and PIWIL4 remain scarce, and in particular, this is the first study to identify the contribution of PIWIL3 and PIWIL4 genes to breast cancer prognosis." (PMID 27177224, 2016). "Knockdown of PIWIL4 revealed its connection to the migration and invasion of breast cancer cells." (PMID 39596284, 2024). "Then, it is still unknown whether PIWIL4 downregulation exclusively affects cell motility of breast cancer cells or also impairs motility of normal cells." (PMID 32357464, 2020). "Piwil4 expression was found to be elevated in both native BC tissues and in the in vitro MDA-MB-231 breast cancer cell line." (PMID 39795985, 2024). "In breast cancer, PIWIL1 and PIWIL3 gene expressions were reported to be upregulated, whereas PIWIL2 and PIWIL4 were downregulated compared with normal breast tissue." (PMID 32987715, 2020). "PIWIL4 is widely expressed in BC tissues and several cell lines derived from Triple-negative breast cancer (TNBC), which promotes cell survival, division, and migration of cancer by activating TGF-β, MAPK/ERK, and FGF signaling pathways, which play key roles in cancer." (PMID 31399034, 2019). "PIWIL4 has been detected at elevated levels in MDA-MB-231 cells, a breast cancer cell line, and PIWIL2 has been proposed as a promising biomarker for breast cancer, being expressed across various disease stages and present in all examined tissue microarray cores." (PMID 39596284, 2024). "From two pairs of matched breast cancer samples, we found that some of the detected CNVs contained some genes that were related to breast cancer, such as PDZK1, XRCC4, Fbxl17, ITGBL1, RORA, BAGE, AMOTL1, RAP80, PIWIL4, CSE1L, and USP18." (PMID 34262604, 2021).
Infertility (5 papers, 2017 to 2025). "Patients from the low infertility risk (LIR) group consistently displayed stronger staining for GTSF1 and PIWIL4 and weaker staining for the L1 transposon compared to HIR samples." (PMID 38166219, 2024). "In the immune-histochemical analysis, patients from the low-infertility-risk group showed coherently stronger staining for GTSF1 and PIWIL4 proteins and weaker staining for the L1 transposon when compared to the high-infertility-risk samples." (PMID 29163975, 2017). "We conducted Sanger sequencing of 620 infertile men with nonobstructive azoospermia and identified potential harmful mutations in the PIWIL4 gene." (PMID 40001600, 2025).
renal cell carcinoma (5 papers, 2019 to 2025). "The expression of the 5 other genes were found to be repressed by over-expressed non-coding RNA or by aberrant methylation of the promoter: GALNT5 in gastric cancer, ADAM6 in lung adenocarcinoma, PIWIL1 and PIWIL4 in lung adenocarcinoma and renal cell carcinoma." (PMID 31568528, 2019). "Clinically, reduced expression of PIWIL4, along with PIWIL1 and PIWIL2, is correlated with unfavorable survival in renal cell carcinoma." (PMID 41208974, 2025). "Downregulation of piRNA pathway genes in cancer may be uncommon but have been reported in testicular germ cell tumor (PIWIL1, PIWIL2, PIWIL4 and DDX4) and renal cell carcinoma (PIWIL1, PIWIL2 and PIWIL4) and now, also in our expression study for PIWIL2, PIWIL4 and TDRD1." (PMID 33374923, 2020).
Azoospermia (4 papers, 2018 to 2025). Absence of any measurable level of sperm,whereby spermatozoa cannot be observed even after centrifugation of the semen pellet. "In summary, we identified a piRNA binding mutation in PIWIL4 that may be involved in human nonobstructive azoospermia." (PMID 40001600, 2025). "Although we could not validate the inheritance models due to the unavailability of parental DNA samples, patients carrying heterozygous mutations in PIWIL4 exhibited nonobstructive azoospermia." (PMID 40001600, 2025).
colon cancer (4 papers, 2010 to 2017). "Li and coworkers also showed that increased PIWIL4 protein levels are significantly associated with the risk of metastasis and prognosis in colon cancer patients." (PMID 22748119, 2012). "The positive expression of EIF2C2 (r = 0.268, P < 0.05), EIF2C3 (r = 0.269, P < 0.05), EIF2C4 (r = 0.242, P < 0.05) and PIWIL4 (r = 0.301, P < 0.01) in colon cancer was associated with the presence of distant metastasis." (PMID 20146808, 2010). "Additionally, high levels of PIWIL2, PIWIL3 and PIWIL4 proteins are correlated with an elevated risk of colon cancer." (PMID 22748119, 2012). "The increased expression level of Piwil4 was related to soft tissue sarcoma and colon cancer metastasis." (PMID 27894076, 2017). "The expression level of Piwil4 protein is increased in soft tissue sarcoma and colon cancer, which is importantly related to poor prognosis and increased risk of metastasis." (PMID 27894076, 2017). "PIWIL1 promotes cancer growth and is associated with increased mortality; increased levels of PIWIL2 have been reported in breast and cervical cancer; and increased levels of PIWIL3 and PIWIL4 have been reported in colon cancer." (PMID 26373553, 2015).
hepatocellular carcinoma (4 papers, 2017 to 2020). A malignant tumor that arises from hepatocytes. "On the other hand, other studies have reported that low PIWIL4 expression was significantly associated with a worse prognosis in hepatocellular carcinoma, soft tissue sarcoma, non-small cell lung cancer and renal cell carcinoma." (PMID 32357464, 2020). "In hepatocellular carcinoma, the nuclear expression of PIWIL4 together with PIWIL2 has been found to confer worse outcome." (PMID 32357464, 2020). "Low levels of PIWIL4 were also found in hepatocellular carcinoma tissues and in other tumors like breast tumors and non-small cell lung cancer compared to the non-cancerous tissues." (PMID 32357464, 2020). "In the hepatocellular carcinoma tissues, Piwil2 showed two expression patterns (nuclear co-expression and nuclear and cytoplasmic expression) and Piwil4 showed four patterns (nuclear co-expression, nuclear and cytoplasmic co-expression, cytoplasmic co-expression, and non-coexpression)." (PMID 27894076, 2017).
male infertility (4 papers, 2021 to 2026). The inability of the male to effect fertilization of an ovum after a specified period of unprotected intercourse. "The loss of core components (e.g., Mili/Piwil2, Miwi2/Piwil4, Mov10l1) causes TE de-repression, DNA damage, meiotic arrest, and male infertility." (PMID 41614953, 2026). "In conclusion, our identification of a piRNA-binding mutation in PIWIL4 provides valuable insights into male infertility, highlighting the impact of species-specific piRNA sequences and targeted retrotransposons." (PMID 40001600, 2025). "Nevertheless, our study expands the possible mechanisms by which human mutations can cause male infertility and lays the foundation for further research into the crucial role of PIWIL4 in both mice and humans." (PMID 40001600, 2025). "To identify PIWIL4-associated mutations associated with human male infertility, we conducted Sanger sequencing of the 20 exons and intron boundaries of the PIWIL4 gene from a cohort of 620 NOA patients." (PMID 40001600, 2025).
cervical cancer (3 papers, 2016 to 2020). A primary or metastatic malignant neoplasm involving the cervix. "On the one hand, high expression of PIWIL4 is found in tumor tissues of colorectal cancer, cervical cancer, gastric cancer and primary and metastatic foci of ovarian cancer compared with their adjacent tissues." (PMID 32357464, 2020).
non-small cell lung carcinoma (3 papers, 2015 to 2020). A group of at least three distinct histological types of lung cancer, including non-small cell squamous cell carcinoma, adenocarcinoma, and large cell carcinoma. "Since expression of PIWI proteins increased resistance to drugs in cervical cancer and in non-small cell lung cancer, we decided to evaluate whether PIWIL3 or PIWIL4 were able to modulate chemoresistance of PC." (PMID 32357464, 2020).
autism (2 papers, 2015 to 2022). Persistent deficits in social interaction and communication and interaction as well as a markedly restricted repertoire of activity and interest as well as repetitive patterns of behavior. "Interestingly, a recent whole exome sequencing study involving simplex families that had a child with autism spectrum disorder showed that de novo mutations of PIWI family members, especially the PIWIL2 and PIWIL4, are strongly associated with autism." (PMID 26104391, 2015). "The role of PIWIL4 in brain is poorly understood, despite recent reports indicating that PIWIL2 and PIWIL4 are associated with autism, and that PIWIL4 helps modulate neuronal differentiation from human embryonal carcinoma cells." (PMID 35015250, 2022).
cholangiocarcinoma (2 papers, 2020 to 2022). A carcinoma that arises from the intrahepatic biliary tree (intrahepatic cholangiocarcinoma) or from the junction, or adjacent to the junction, of the right and left hepatic ducts (hilar cholangiocarcinoma). "Previous studies reported that PIWIL4 was probably a pivotal biomarker for predicting prognosis and immune landscape of cholangiocarcinoma." (PMID 36160408, 2022). "Our analysis suggests that expression of DEPDC1, FUT4, MDK, PACS1, PIWIL4, miR-22, miR-551b, and DNA methylation of cg27362525 and cg26597242 could be explored further as potential biomarkers of cholangiocarcinoma." (PMID 33193605, 2020).